IFNG (interferon gamma)
Diseases named in the same sentence as IFNG in open-access papers (continued):
Sharing a sentence is not in itself a finding about the gene and the disease.
Immunodeficiency (continued). "Underlying immune disorders were identified only in the SGM cases [genetic (n = 2), HIV (n = 1), sarcoidosis (n = 1), and anti-interferon-gamma antibodies (n = 1)]." (PMID 38742044, 2024). "Most of localized and disseminated BCG infections have occurred in patients with combined immunodeficiency and with inborn defects of the IFNγ/IL12 axis which found to be in agreement with previously reported findings." (PMID 35529857, 2022). "UC is a TH2 type immune disease, with up-regulation of IL-5, whereas CD is a TH1 type immune disease, showing high levels of interferon gamma (IFN-), IL-12, and tumor necrosis factor alpha (TNF-α)." (PMID 32851982, 2021). "We also investigate the potential of clinically available immune stimulants, Interferon Gamma (IFN-γ) and Granulocyte-Macrophage Colony-Stimulating Factor (GM-CSF), to reverse features of post-operative immune-dysfunction." (PMID 30212506, 2018). "We have learned from the described immunodeficiencies that the IL-17 pathway is fundamental for mucosal antifungal host defense, while neutrophil function and IFNγ and GM-CSF are essential for preventing invasive fungal infection." (PMID 26845151, 2016). "Recently, the cell-mediated immune deficiency in these HIV-negative, adult-onset immunodeficient patients was linked to the presence of autoantibody to interferon-gamma (IFN-γ)." (PMID 24086734, 2013). "The final diagnosis was immunodeficiency secondary to the production of autoantibodies against interferon-gamma, which resulted in a post-obstructive pneumonia and disseminated infection of M. colombiense." (PMID 23336346, 2013). "This occurs as a result of immune dysfunction, characterized by changes in the circulating levels of cytokines via increased inflammatory mediators like IL‐1β, IL‐6, Interferon gamma (IFN‐γ), TNF‐α, and reduced levels of cytokines like adiponectin and IL‐10, which have an anti‐inflammatory function." (PMID 40838278, 2025). "In addition, interferon-gamma (IFN-γ) has been tried in limited situations to improve immune dysfunction." (PMID 40555121, 2025). "Interferon-gamma responses to spike and peptide mix stimulation, immunoglobulin response post primary vaccination, vaccine response score and COVID-19 disease infection severity of individuals with immunodeficiency." (PMID 37033955, 2023). "Besides malignancy, the most common immunodeficiencies were adult-onset immunodeficiency induced by anti-interferon-gamma autoantibody, SLE, and vasculitis." (PMID 35665363, 2022). "When talaromycosis was confirmed in a HIV-negative patient and no other obvious immunocompromised status was found, other primary immunodeficiency conditions, such as presence of anti-interferon-gamma autoantibody, hyper-IgE syndrome and hyper-IgM syndrome, should be looked for." (PMID 34436175, 2021). "BCG vaccine reactivation has an important effect on the prognosis of combined immunodeficiencies, but this vaccine also helps to identify interferon gamma/interleukin 2 axis defects with BCG-itis and to determine T-lymphocyte function with a positive tuberculin (purified protein derivative) test." (PMID 28404538, 2017). "Such cells could preferentially develop into IFNγ-producing cells in human immune diseases, such as Crohn's disease." (PMID 26549640, 2015). "Its deletion causes immunodeficiency because of B-lymphocytes produce lower levels of immunoglobulins, tumor necrosis factor (TNF) and lymphotoxin, and because of T-lymphocytes produce lower levels of interferon-gamma (IFNγ) and interleukin-12 (IL-12) promoting differentiation to Th2 phenotype." (PMID 33330058, 2020). "Anti-interferon gamma autoantibodies (anti-IFN-γ autoAbs) neutralize the IFN-γ-mediated functions, contributing to immunodeficiency." (PMID 35534543, 2022).
Immunodeficiency (continued). "Conversely, in the case of immunodeficiency, a pro-inflammatory response including Th1 CD4, cytotoxic CD8, NK cells, and IFNγ release seems beneficial for M1 macrophage activation, despite the impact of inflammation on lung tissue." (PMID 34436164, 2021). "For these 136 HIV-negative patients, 62 were confirmed to have other forms of immunodeficiencies, such as anti-interferon gamma autoantibodies and post-renal/liver transplantation." (PMID 41422439, 2025). "Specifically, studies have shown that the activation of 5-HT1A and 5-HT2A serotonin receptors suppresses the production of interferon-gamma (IFN-γ) and TNF-α, weakening the cellular immune response and promoting the development of immune dysfunction under chronic stress." (PMID 39857306, 2025). "Assessment for an underlying immunodeficiency was negative for HIV and autoantibodies against interferon-gamma (IFN-γ) or granulocyte-macrophage colony-stimulating factor (GM-CSF)." (PMID 38609851, 2024). "The observed lack of circulating IFNγ in the plasma of patients suggests either severe immune dysfunction or exhaustion." (PMID 36742994, 2022). "However, selected mechanistically well-characterized microbiota-immune system interactions are depicted in some immunodeficiency disorders, like adult-onset immunodeficiency (AOID) with anti-interferon-gamma autoantibodies (anti-IFN-γ AAbs)." (PMID 35650243, 2022). "Further investigation revealed reduced interferon-gamma production but no other significant immune dysfunction." (PMID 30453935, 2018). "The interplay between IFNγ released from immune cells and PACAP is of importance in brain inflammation and may affect the regeneration and recruitment of NPCs in immune diseases." (PMID 20559421, 2010). "Overall, these data suggest that both IFNγ and IL-17A were required for complete host protection and pulmonary containment of the WT strain in C. neoformans Δsgl1-vaccinated mice regardless of T cell immunodeficiency." (PMID 36229573, 2022). "It is possible that in children currently experiencing an episode of OM, the reduced IFNγ+ CD4+ T cell response to NTHi challenge is a reflection of lymphocyte exhaustion (or deployment of these antigen-reactive cells to the ear) rather than an inherent cell-mediated immunodeficiency." (PMID 29621281, 2018). "Autoantibodies to interferon-gamma (IFN-γ) are known to be involved in disseminated NTM disease, although anti-IFN-γ antibodies are mainly seen in immunocompetent patients rather than those with immunodeficiency." (PMID 36717786, 2023). "The immune dysfunction is not probably due to impaired T-cell function, since neither CD4+ T-cell dependent IFNγ producing cell number nor IL10 producing regulatory T-cells resulted different outcomes in response to PMA-Ionomycin and PHA-LPS stimulation, respectively." (PMID 28170444, 2017). "The increased amount of CD4+CD28− T lymphocytes in patients with MHE indicates stronger immune dysfunctions than in patients without MHE, with persistent immune activation, increased production of TNFα, IFNγ and of molecules which may damage endothelial cells and tissues." (PMID 28751644, 2017).
multiple sclerosis (198 papers, 2005 to 2026). A progressive autoimmune disorder affecting the central nervous system resulting in demyelination. "IFNγ and IL-17 are highly inflammatory cytokines, and both implicated in CNS-related disorders such as multiple sclerosis." (PMID 33676561, 2021). "While beyond the scope of the present study, future studies could manipulate IFNγ signaling to promote or limit microglial mobilization toward lesions associated with vascular injury or multiple sclerosis, and determine if they hold any therapeutic benefit." (PMID 37428916, 2023). "IFNγ-induced signaling pathway activation was described in CNS fibrotic cells in a mouse model of multiple sclerosis." (PMID 41280671, 2025). "GRIM-19 ameliorates multiple sclerosis through reciprocal regulation of IFNγ/Th1 and IL-17A/Th17 cells in a mouse model of experimental autoimmune encephalomyelitis." (PMID 36387896, 2022). "Human BMMSCEVs stimulated by interferon-gamma (IFN-γ) exhibited a reduction in demyelination and neuroinflammation, thereby improving motor skills, in a multiple sclerosis experimental autoimmune encephalomyelitis (EAE) mouse model." (PMID 33668707, 2021). "Pre-exposure of healthy brain to IFNγ reduces subsequent demyelination in animal models of multiple sclerosis." (PMID 34337600, 2021). "One of the most important pathways in pathogenesis of multiple sclerosis is the IFNγ/STAT1/T-bet pathway of Th1 cells." (PMID 33271810, 2020). "Supporting this finding are data describing an increase in IFNγ-producing Tregs in patients with multiple sclerosis and type-1 diabetes." (PMID 29176976, 2017). "There is evidence that GM-CSF can be produced by CD161+IFNγ+ ex-Th17 cells in the joint of some RA patients and by peripheral blood Th17 cells in patients with multiple sclerosis." (PMID 28488248, 2017). "Results showed that CD19+ cells expressing IFNγ were significantly increased in patients with a diagnosis of PP multiple sclerosis compared to SP, RR, BEMS individuals and HC (p < 0.005)." (PMID 27412504, 2016). "We thus next investigated this possibility in a small cohort of samples from healthy controls or individuals with either multiple sclerosis (MS) or Spondylarthritis (SpA) using M0 (unstimulated), M1 (LPS/IFNγ) or M2 (IL-4/IL-10/TGF-β) polarization protocols." (PMID 24521472, 2014). "We found, that patients suffering from multiple sclerosis during an acute relapse showed a significant increase of IFNγ (three control samples vs. three MS samples)." (PMID 23162429, 2012). "ELISA results demonstrated that NK cells were activated by ALS patient sera to produce augmented amounts of IFNγ, while inflammatory bowel disease patient, multiple sclerosis patient or healthy control sera induced lower IFNγ production." (PMID 22666317, 2012). "For example, in a murine model of multiple sclerosis, neutralization of IFNγ resulted in inflammatory immune responses." (PMID 22423982, 2012). "Administration of exogenous interferon-γ (IFNγ) aggravates the symptoms of multiple sclerosis (MS), whereas interferon-β (IFNβ) is used for treatment of MS patients." (PMID 21261980, 2011). "The levels of IFNγ increase in brain in different diseases, such as multiple sclerosis and encephalitis and following immune reactions." (PMID 20559421, 2010). "Microglia can release both TNFa and IFNg in inflammatory conditions such as demyelination in multiple sclerosis, which may trigger the release of inflammatory signals for the oligodendrocytes." (PMID 39091874, 2024). "In a study with exosomes, the effect of exosomes secreted from MSCs in the therapy of multiple sclerosis has been evaluated and it has been reported that exosomes stimulated by IFNγ (IFNγ-Exo) reduce demyelination and neuro-inflammation and increase the regulatory T cells in spinal cords." (PMID 38720930, 2024).
multiple sclerosis (continued). "In our work, we evaluated the profile of cytokines and chemokines, as well as the production of double positive CD4+ T cells for the production of IFNγ IL-17 in patients with multiple sclerosis, at different stages of the disease and undergoing different treatments." (PMID 36140164, 2022). "Additionally, sesame oil reduces significantly the concentrations of IFNG in multiple sclerosis patients." (PMID 33578642, 2021). "Indeed, IFNγ+ Tregs have been documented in healthy donors but are enriched in various autoimmune conditions including multiple sclerosis and T1D, and have impaired suppressive capacity." (PMID 32351504, 2020). "Similarly, CXCL16 blockade reduced serum IFNγ levels and in vitro antigen recall responses in a mouse model of multiple sclerosis." (PMID 27471636, 2016). "Significantly elevated IFNγ levels were found during relapses in multiple sclerosis (n = 3) and we also found increased levels in individual patients suffering from peripheral nervous plexus affections, Alzheimer dementia, viral myelitis, or stroke (n = 1, respectively)." (PMID 23162429, 2012). "Therefore, we measured the concentration of IFNγ in cerebrospinal fluid (CSF) specimens, taken after lumbar punction from patients suffering from multiple sclerosis, peripheral nervous plexus affections, Alzheimer dementia, viral myelitis, or stroke." (PMID 23162429, 2012). "CD20+ T cells have been identified in individuals with multiple sclerosis, and although CD20 expression is usually associated with B cells, its expression on T cells has been linked to activated memory T cells that produce proinflammatory cytokines such as IFNγ." (PMID 41273416, 2026). "Inflammatory environments induce the generation of dysfunctional IFNγ+T‐bet+FOXP3+ Th1‐like Tregs, which show defective function and are found in autoimmune conditions including multiple sclerosis (MS)." (PMID 39444366, 2025). "For instance, in a mouse model of multiple sclerosis, abnormal NR4A2 expression enhanced the promoter activity of interleukin-17 and interferon-gamma genes, resulting in excessive cytokine production." (PMID 39512681, 2024). "Assessing 15 representative signature genes in patients with multiple sclerosis, we find that TH1/17 cells have elevated expression of CXCR3 and reduced expression of IFNG, CCL3, CLL4, GZMB, and IL10 compared to healthy controls." (PMID 29150604, 2017). "A similar inhibitory effect of human NK2 cells on the production of IFNγ by T cells was also reported for healthy individuals' NK cells that were induced to express the NK2 phenotype, and for NK2 cells obtained from multiple sclerosis patients in remission." (PMID 20459787, 2010). "CD4 Stat−/− mice do not develop EAE (a mouse model of multiple sclerosis) or EAU (autoimmune experimental uveoretinitis), have impaired Th17 cell differentiation and an increase in T cells expressing Foxp3, IL-10, IL-4 and IFNγ." (PMID 33271810, 2020).
co-infection (197 papers, 2008 to 2026). "In fact, co-infection suppresses peak joint pathology of CHIKV infection by limiting the infiltration of pathogenic virus-specific IFNγ (Th1)-producing CD4+ T cells in the joints." (PMID 30254309, 2018). "It is plausible that the household contacts with these co-infections were unable to produce adequate amounts of IFNγ making it difficult to see an association with LTBI." (PMID 25372043, 2014). "Furthermore, helminth co-infection is associated with more advanced disease in tuberculosis patients and with reduced production of IFNγ but increased IL-10." (PMID 36753434, 2023). "Our study therefore suggests that in HIV patients with a low CD4+ T cell count, a HCMV co-infection generates an aggravated IFNγ response which thereby leads to the activation of the CXCL9/10/11-CXCR3 chemokine axis." (PMID 35538132, 2022). "Our findings demonstrated that co-infection resulted in higher levels of mRNA levels of Gal-1, Gal-3, IFNγ, IL-6, and iNOS in the liver of co-infected mice compared with PbANKA-mono-infection." (PMID 32883347, 2020). "In contrast, pre-Py17x (−4 dpi) + CHIKV co-infection in IFNγ-/- mice induced joint swelling similar to WT CHIKV-infected mice at early acute infection of 1–4 dpi." (PMID 30254309, 2018). "To verify these effects observed in pre-Py17x co-infected IFNγ-/- mice, we performed pre-Py17x co-infection of WT mice with IFNγ neutralization during the early acute phase (−4 dpi to 4 dpi) of the disease." (PMID 30254309, 2018). "Co‐infection with CHIKV induced higher splenic IFNγ levels that lead to high local levels of CXCL9 and CXCL10." (PMID 29113976, 2018). "This occurs through the induction of higher splenic IFNγ during co‐infection, leading to higher local levels of CXCL9 and CXCL10 that retains the CXCR3‐expressing CD8+ T cells in the spleen." (PMID 29113976, 2018). "We also postulate that this co-infection induces an intense, self-perpetuating cytokine cascade beginning with the local production of TNFα and interferon gamma (IFNγ) in response to M. tuberculosis in the lung." (PMID 29770360, 2018). "Pre-Py17x co-infection was excluded due to the impact of Plasmodium induced IFNγ at the point of CHIKV infection that suppressed early acute CHIKV viral load." (PMID 30254309, 2018). "To further demonstrate the causal relationship between IFNγ and CXCL9/CXCL10 induction in the co‐infected mice, we performed co‐infection in IFNγ−/− mice." (PMID 29113976, 2018). "In conclusion, we have shown that IL-12 and IFNγ suppressed Th2 responses during H. polygyrus and P. chabaudi co-infection." (PMID 26147567, 2015). "Conversion of Th2 cells was dependent upon IL-12 and IFNγ-signaling, and blockade of these cytokines during co-infection preserved the Th2 response." (PMID 26147567, 2015). "This is attributable to the comparable levels of interferon gamma (IFN-γ) secreted during co-infection and correlated with protective immunity." (PMID 26377900, 2015). "Finally, we tested whether the factors promoting IFNγ in the adoptive transfer model, IL-12 and IFNγ, were responsible for the loss of Th2 cells and type-2 immunity during H. polygyrus and P. chabaudi co-infection." (PMID 26147567, 2015). "Helmby observed exacerbated liver pathology with significantly increased IFNγ and mortality during H. polygyrus and Plasmodium co-infection." (PMID 26147567, 2015). "A systematic review of the interferon-gamma release assays in HIV/TB co-infection has noted a sensitivity of 80%." (PMID 22558946, 2012). "The early IFNγ inflammatory signal observed both in single and co-infection was a host response to the mucosa damage by helminth establishment, and probably bacteria and microflora infiltration from the lumen." (PMID 22253585, 2012). "In addition, it led to a significant increase in IFNγ secretion compared to co-infection with Ad5/3-tE and Ad5/3-DM." (PMID 41552759, 2026).